SCTR (secretin receptor)
Description:
G protein-coupled receptor activated by secretin (SCT), which is involved in different processes such as regulation of the pH of the duodenal content, food intake and water homeostasis. Ligand binding causes a conformation change that triggers signaling via guanine nucleotide-binding proteins (G proteins) and activates cAMP-dependent pathway. Upon binding to secretin, regulates the pH of the duodenum by (1) inhibiting the secretion of gastric acid from the parietal cells of the stomach and (2) stimulating the production of bicarbonate (NaHCO(3)) from the ductal cells of the pancreas (By similarity). In addition to regulating the pH of the duodenal content, plays a central role in diet induced thermogenesis: acts as a non-sympathetic brown fat (BAT) activator mediating prandial thermogenesis, which consequentially induces satiation. Mechanistically, secretin released by the gut after a meal binds to secretin receptor (SCTR) in brown adipocytes, activating brown fat thermogenesis by stimulating lipolysis, which is sensed in the brain and promotes satiation. Also able to stimulate lipolysis in white adipocytes. Also plays an important role in cellular osmoregulation by regulating renal water reabsorption. Also plays a role in the central nervous system: required for synaptic plasticity (By similarity).
Synonyms: SECR; SR
Tractability: Antibody: its Gene Ontology location is reachable by antibodies, with high confidence; UniProt places it where antibodies can reach, with medium confidence; UniProt predicts a signal peptide or a membrane-spanning region. PROTAC: a small molecule that binds it is known. Other modalities: an approved drug acts on it.
Target class: Family B G protein-coupled receptor; Membrane receptor; Peptide receptor (family B GPCR); Glucagon-like receptor; Secretin receptor receptor
Gene: Protein-coding gene on chromosome 2 (119,439,839 to 119,525,301, reverse strand). Ensembl gene ENSG00000080293.
Subcellular location: Cell membrane; Basolateral cell membrane
Pathways (Reactome):
Signal Transduction: G alpha (s) signalling events; Glucagon-type ligand receptors
Gene Ontology:
Molecular function: peptide hormone binding; secretin receptor activity; G protein-coupled peptide receptor activity; G protein-coupled receptor activity; transmembrane signaling receptor activity
Biological process: adenylate cyclase-activating G protein-coupled receptor signaling pathway; G protein-coupled receptor signaling pathway; adenylate cyclase-modulating G protein-coupled receptor signaling pathway; diet induced thermogenesis; intracellular water homeostasis; regulation of appetite; regulation of synaptic plasticity; response to nutrient levels; cell surface receptor signaling pathway
Cellular component: cytoplasmic microtubule; basolateral plasma membrane; plasma membrane; membrane
Genetic constraint (gnomAD): Loss-of-function variants: 47 observed, 43.65 expected, observed/expected ratio (o/e) 1.08, 90% interval 0.85 to 1.37. The upper end of that interval is the gene's LOEUF score, 1.37, which puts it in group 5 of 6, group 1 being the genes least tolerant of losing a copy. Missense variants: 467 observed, 446.23 expected, observed/expected ratio (o/e) 1.05, 90% interval 0.97 to 1.13. Synonymous variants: 179 observed, 178.69 expected, observed/expected ratio (o/e) 1, 90% interval 0.89 to 1.13.
Homologues: Orthologues: chimpanzee SCTR (99% identical), macaque SCTR (98% identical), dog SCTR (85% identical), pig SCTR (85% identical), rabbit SCTR (82% identical), rat Sctr (82% identical), guinea pig SCTR (80% identical), mouse Sctr (80% identical), tropical clawed frog SCTR (53% identical). Paralogues in human: VIPR1 (48% identical), ADCYAP1R1 (47% identical), VIPR2 (45% identical), PTH1R (41% identical), GHRHR (40% identical), GLP1R (39% identical), GCGR (38% identical), PTH2R (38% identical), GLP2R (37% identical), GIPR (37% identical), CALCRL (28% identical), CALCR (27% identical), and 30 more.
Diseases named in the same sentence as SCTR in open-access papers:
SCTR is named in the same sentence as 34 diseases in open-access papers, as found by Europe PMC text mining. Sharing a sentence is not in itself a finding about the gene and the disease. The quoted sentences say what the papers report.
adenoma (3 papers, 2009 to 2024). A neoplasm arising from the epithelium. "In colorectal carcinoma (CRC), a massive methylation of the SCTR gene with lower methylation levels in precancerous lesions (polyp, adenoma) and highest levels in carcinoma has recently been reported." (PMID 35327338, 2022). "Recent research has also revealed the high accuracy of secretin receptor (SCTR) methylation in detecting both CRC and adenomas." (PMID 38464391, 2024). "Hypermethylation of at least one of the CpG islands analysed (EN1, SCTR, INHBB) occurred in most carcinomas (90%), with EN1 methylated in 73 and 40% of carcinomas and adenomas, respectively." (PMID 19384295, 2009).
cholangiocarcinoma (3 papers, 2022 to 2025). A carcinoma that arises from the intrahepatic biliary tree (intrahepatic cholangiocarcinoma) or from the junction, or adjacent to the junction, of the right and left hepatic ducts (hilar cholangiocarcinoma). "Overexpression of SCTR has been described for gastrinomas, carcinoid tumors of the lung and cholangiocarcinoma." (PMID 35327338, 2022).
colorectal cancer (3 papers, 2009 to 2025). A primary or metastatic malignant neoplasm that affects the colon or rectum. "The secretin receptor (SCTR), identified as a marker of poor prognosis and metastasis in colorectal cancer, has been shown to be a key carrier of N‐glycans with sialylated Lewis antigens." (PMID 39508360, 2025). "The three CpG islands associated with the promoter region of the genes EN1, SCTR and INHBB mapping to 2q14.2 have been identified earlier to be hypermethylated in colorectal cancer." (PMID 19384295, 2009).
Hepatic fibrosis (3 papers, 2021 to 2022). The presence of excessive fibrous connective tissue in the liver. "Among the different liver cells, SCTR was localized to cholangiocytes and associated with liver fibrosis and DR both at the time of PE and after SPE." (PMID 35508528, 2022). "We extend these previous observations by demonstrating overexpression of SCTR in BA livers with a close correlation to liver fibrosis both at PE and after SPE." (PMID 35508528, 2022). "Liver SCTR expression localized in cholangiocytes and correlated positively with liver fibrosis, DR, and transcriptional markers of fibrosis (ACTA2) and cholangiocytes (KRT7, KRT19) both at PE and after SPE." (PMID 35508528, 2022). "Recently, in animal models, cholangiocytes associated with the secretin (SCT)/secretin receptor (SCTR) axis have been linked to NAFLD pathogenesis, playing an important role in biliary injury and hepatic fibrosis." (PMID 34199535, 2021). "In conclusion, we demonstrate significant liver overexpression of SCTR, which predicted clearance of jaundice and NLS in BA and correlated closely with liver fibrosis both at the time of PE and during postoperative follow-up after SPE." (PMID 35508528, 2022).
gastrinoma (2 papers, 2022 to 2025). "In disease, a secretin receptor (SCTR) was found to occur as a splice variant in gastrinoma and pancreatic adenocarcinoma." (PMID 35327338, 2022).
Obesity (2 papers, 2024 to 2025). Accumulation of substantial excess body fat. "Other GPCRs involved in neurohormonal signalling and associated with obesity and insulin resistance, such as OPRK1 and ADRB2, and receptors for peptide hormones, including somatostatin (SSTR1/2/5) and secretin (SCTR), were also enriched in K cells." (PMID 39441374, 2025).
pancreatic cancer (2 papers, 2012 to 2022). "The aim of this study was to characterize SCTR expression in esophageal and pancreatic cancer, demonstrating for the first time high SCTR overexpression in these tumor types." (PMID 35327338, 2022). "The contributing genes to this pathway, e.g. CCKBR, CHRM5, EDNRA, LPAR1, SSTR2/3, and SCTR, have diverse functions in regulating the endocrine and exocrine functions of the pancreas, which are highly relevant to pancreatic cancer." (PMID 23056513, 2012).
pancreatic ductal adenocarcinoma (2 papers, 2022 to 2025). An infiltrating adenocarcinoma that arises from the epithelial cells of the pancreas. "In addition to esophageal cancer, expression of SCTR was evaluated in pancreatic ductal adenocarcinoma (PDAC)." (PMID 35327338, 2022).
breast carcinoma (1 paper, 2014). "In breast cancer, FLRT2 and SCTR are good candidates for novel markers; the expression of which is known to be down regulated." (PMID 24842468, 2014).
cholestasis (1 paper, 2023). Impairment of the bile flow caused by obstruction within the liver, or outside the liver in the bile duct system. "The secretin (Sct)/secretin receptor (SR) axis (expressed only by cholangiocytes) regulates liver phenotypes in cholestasis." (PMID 36624475, 2023).
chronic pancreatitis (1 paper, 2022). A chronic inflammatory process causing damage and fibrosis of the pancreatic parenchyma. "This retention of plasma-membrane localization was also found in PDAC tissues, where high SCTR overexpression was found in 65 of 70 investigated PDAC tissues, while islet cell tumors and chronic pancreatitis proved to be low in SCTR expression." (PMID 35327338, 2022).
cyst (1 paper, 2021). A sac-like closed membranous structure that may be empty or contain fluid or amorphous material. "Both monolayer and cyst populations expressed the core functional transporter genes CFTR, SLC4A2, SCTR, and primary cilia related genes." (PMID 34764255, 2021).
esophageal cancer (1 paper, 2022). A primary or metastatic malignant neoplasm involving the esophagus. "For all three subtypes of esophageal cancer, a strong SCTR overexpression was detected, most prominent in ESCC." (PMID 35327338, 2022). "Consequently, and in contrast to the findings in this study for PDAC and esophageal cancer, SCTR expression in CRC may be strongly reduced rather than upregulated." (PMID 35327338, 2022).
liver cancer (1 paper, 2022). An epithelial or non-epithelial malignant neoplasm that arises from the liver. "As liver cancer is considered an immunogenic tumor, the relationship between the expression of DOCK2, SCTR, TANC1, ALKBH7, FREM2, and GNG4 and the levels of immune cells and stromal cells was assessed." (PMID 35620462, 2022).
lung carcinoma (1 paper, 2020). "For example, secretin receptor genes were over-expressed in LS compared to SS samples, and its role in lung cancer has been described by some authors." (PMID 32587780, 2020).
lung fibrosis (1 paper, 2025). "In conclusion, our data identify SCTR as a spatially restricted, macrophage‐specific regulator of silica‐induced lung fibrosis." (PMID 40967637, 2025).
Osteopenia (1 paper, 2024). Osteopenia is a term to define bone density that is not normal but also not as low as osteoporosis. "Cre-mediated KD of SCTR in VMH reproduced the osteopenia phenotype seen in ShSCT and SCTVMH−/− mice." (PMID 38310104, 2024). "Similarly, VMH-specific KD of SCTR in DIO mice also led to significantly more serious osteopenia accompanied by the upregulation of sympathetic tone." (PMID 38310104, 2024).
Polyuria (1 paper, 2014). An increased rate of urine production. "Our research group for the first time reported polydipsia and polyuria in SCTR KO mice under both normal and hyperosmolality conditions." (PMID 24904528, 2014).
renal carcinoma (1 paper, 2021). A carcinoma arising from the epithelium of the renal parenchyma or the renal pelvis. "Interestingly, the gene probes targeting FGF17, PRKCG, SSTR1, and SCTR predicted potential targeted agents for renal cancer metastasis and adjuvant immunotherapy, including 5224221, calmidazolium, and sulfasalazine." (PMID 35155566, 2021).
silicosis (1 paper, 2025). Silicosis is a respiratory disease caused by breathing in (inhaling) silica dust. "Furthermore, investigation into human silicosis tissues could determine whether SCTR expression correlates with disease stage or prognosis." (PMID 40967637, 2025).
type 2 diabetes (1 paper, 2018). "Nine genes not previously reported to be associated with type 2 diabetes were significantly dysregulated in our organ donor and PPP cohorts (ANKRD23/39, ASCL2, HHATL, NSG1, PCDH20, SCTR, CD44, FAM102B and FBXO32)." (PMID 29185012, 2018).
cancer (6 papers, 2009 to 2025). A tumor composed of atypical neoplastic, often pleomorphic cells that invade other tissues. "Additional GPCRs reported to promote proliferation and migration of cancer cells included secretin receptor SCTR, and lysophosphatidic acid (LPA) receptor LPAR247,48." (PMID 36220861, 2022). "In summary, we found significant differences in the expression of FGF17, PRKCG, SSTR1, and SCTR in cancer, which are correlated with immune response and adjuvant therapy." (PMID 35155566, 2021). "The dysregulation of SCTR had been reported, which relates to a few cancers." (PMID 36772473, 2023). "Furthermore, we have verified SCTR as a primary carrier of sLe antigens, proposing that these glycoepitopes might confer cancer specificity to the glycoprotein and enable adhesion to E‐selectin." (PMID 39508360, 2025). "Secretin receptor (SCTR), also known as GPCR, was abnormally expressed in many cancers to affect the proliferation of tumor cells." (PMID 35155566, 2021).
tumor (6 papers, 2009 to 2025). "Approximately 70% of the cases positive for SCTR, either tumors or metastases, coexpressed sLe antigens in the same tumor area." (PMID 39508360, 2025). "SCTR therefore is considered a candidate target for molecular tumor imaging as well as for peptide receptor radioligand therapy (PRRT) in a number of oncological indications." (PMID 35327338, 2022). "Early stage tumours showed a higher proportion of methylated genes (P=0.020) and SCTR was the gene exhibiting the higher differences (P=0.015)." (PMID 19384295, 2009). "Interestingly, high SCTR overexpression was demonstrated in tumor tissues of all histopathological gradings, with only slightly lower values for less differentiated tumors." (PMID 35327338, 2022). "Low expression of SCTR could stimulate tumor cell proliferation through the PI3K/AKT signaling pathway, and the combination of PI3K inhibitors and tumor chemoradiotherapy had been shown to inhibit tumor proliferation." (PMID 35155566, 2021). "Subsequently, through OCLR scores, it was further confirmed that the expressions of FGF17, PRKCG, SSTR1, and SCTR were different in KIRC, which might lead to tumor metastasis by promoting tumor dedifferentiation." (PMID 35155566, 2021).
SCTR also shares sentences with these, for which no sentence is quoted: bile duct cancer (1 paper); carcinoid tumors of the lung (1); cardiovascular disease (1); inherited retinal dystrophy (1); Insulin resistance (1); islet cell tumors (1); migraine (1); pancreatic adenocarcinoma (1); polyp (1); primary biliary cholangitis (1); primary sclerosing cholangitis (1).